EGFR (epidermal growth factor receptor)
Diseases named in the same sentence as EGFR in open-access papers (continued):
Sharing a sentence is not in itself a finding about the gene and the disease.
lung adenocarcinoma (continued). "Activating mutations in EGFR are observed in up to 50% of lung adenocarcinomas in Asians and approximately 10% of Caucasians with NSCLC." (PMID 26919104, 2016). "Second, in our study, female lung adenocarcinoma patients had a higher EGFR mutation rate than that of male patients." (PMID 27191886, 2016). "With respect to the histological types, the EGFR mutation rate among the lung adenocarcinomas (46.9%), was significantly higher than that observed in the squamous cell carcinomas (10.1%) (P<0.01)." (PMID 27322143, 2016). "The current study retrospectively investigated the clinical outcomes of 532 lung adenocarcinoma patients harboring EGFR 19 del or L858R mutation after first-generation EGFR-TKI treatment." (PMID 27001083, 2016). "This study revealed that the status of EGFR mutation in lung adenocarcinomas is relatively consistent between primary and metastatic sites compared to K-ras mutation." (PMID 27070580, 2016). "With regards to the EGFR mutation frequency and spectrum, we only evaluated patients with lung adenocarcinoma to eliminate the confounding effect of different histology." (PMID 27449093, 2016). "Formalin-fixed, paraffin-embedded samples from 456 patients with wild-type EGFR lung adenocarcinoma were analyzed for HER-2 mutations by amplification-refractory mutation system (ARMS), and HER-2 protein expression was evaluated by immunohistochemistry." (PMID 27793199, 2016). "Here, for the first time, we have presented representative data for Croatian patients with lung adenocarcinomas, and we demonstrate a higher prevalence of the specific L858R mutation in the EGFR gene, as well as a higher prevalence of KRAS mutations." (PMID 27655296, 2016). "The findings revealed that 21 of 38 (55.3%) lung adenocarcinomas with clear cell component were detected harboring mutations in our tested genes, including 52% (11/21) EGFR mutations." (PMID 27013585, 2016). "Activating mutations in the epidermal growth factor receptor (EGFR) gene have been shown to be associated with a dramatic clinical response to EGFR tyrosine kinase inhibitors (EGFR-TKIs) in patients with lung adenocarcinomas." (PMID 27488410, 2016). "The results indicated that GA + AA genotypes of IGF1R rs2229765 were significantly associated with EGFR mutation in female lung adenocarcinoma patients (odds ratio (OR) = 0.39, 95% confidence interval (CI) = 0.17–0.87)." (PMID 27213344, 2016). "Among the three groups, we evaluated only patients with stage IIIB–IV lung adenocarcinoma who had EGFR mutations (n = 126), KRAS mutations (n = 35), or ALK rearrangements (n = 47) to avoid the influence of confounding factors such as tissue type and staging." (PMID 27518729, 2016). "The prognostic role of epidermal growth factor receptor (EGFR) mutations in patients with lung adenocarcinomas remains controversial and the association between EGFR mutations and stage at the time of the initial diagnosis is debatable." (PMID 27861565, 2016). "We describe a case of a 49-year-old man with lung adenocarcinoma harboring L858R point mutation at the exon 21 of the epidermal growth factor receptor (EGFR)." (PMID 27488410, 2016). "A lung adenocarcinoma cell line (PC9) with an activating EGFR mutation was treated with escalating sublethal doses of gefitinib, resulting in resistant cell lines (PC9-GR), harbouring EGFR T790M mutation." (PMID 26924553, 2016). "The variation in the survival of patients with advanced lung adenocarcinoma is associated with multiple factors (EGFR mutation status, ECOG performance status, metabolism variables, serum markers, and sex)." (PMID 27336755, 2016). "Our prevalence of 15.7 % in EGFR-mutated lung adenocarcinomas seems to be among the higher rates in European countries and is closer to what was reported in the Russian study by Moiseyenko, where the prevalence was 19.8 %." (PMID 27655296, 2016).
lung adenocarcinoma (continued). "The study assessing molecular characteristics of lung adenocarcinomas, which harbor EGFR, KRAS mutations or ALK rearrangements as well as triple negative adenocarcinomas, dominated the top 10 alignment outcomes." (PMID 26967245, 2016). "Several studies have demonstrated that risk factors for BM in NSCLC, but there were no reports on the risk factors for developing BM during the course of EGFR-TKIs therapy from EGFR-mutated advanced lung adenocarcinoma." (PMID 27626317, 2016). "In one study in China, the authors reported EGFR mutations in 66.3 % of consecutively collected lung adenocarcinomas, which were analyzed by sequencing." (PMID 27655296, 2016). "In the present study, we retrospectively evaluated the association between EGFR mutations and stage at diagnosis in all stages of lung adenocarcinomas, adjusting for screening." (PMID 27861565, 2016). "Transformation to small cell lung cancer(SCLC), although uncommonly seen, has been associated with resistance to EGFR-TKI therapy in lung adenocarcinomas." (PMID 27488410, 2016). "The 92-gene assay resulted in a diagnosis of lung adenocarcinoma (probability = 90%) with an EGFR L858R mutation, enabling eligibility for EGFR targeted therapy options." (PMID 27034010, 2016). "For instance, for lung adenocarcinoma, the Northeast Asian population has a higher prevalence of activating mutation of the EGFR tyrosine kinase domain." (PMID 27050078, 2016). "Consistent with the result above, our analysis for 134 patients with EGFR-mutated advanced lung adenocarcinoma also demonstrated that CEA ≥ 23 ng/mL was associated with an increased risk for developing BM." (PMID 27626317, 2016). "Driver mutations in EGFR (exon 19 deletion or exon 21 L858R substitution) are found in 15–20% of all lung adenocarcinomas (ACs) that account for the largest group of lung cancer patients." (PMID 27938382, 2016). "We report on the long-term results of first-line treatment with erlotinib in Caucasian patients with advanced adenocarcinoma of the lung that have a somatic EGFR mutation in their tumor." (PMID 27032107, 2016). "EGFR, the second most recurrently mutated oncogene in lung adenocarcinoma, showed a much more dispersed pattern of mutational events across its protein-coding domains." (PMID 27933110, 2016). "EGFR mutation was shown to be an independent predictive and prognostic risk factor of BM for patients with lung adenocarcinoma, as well as a positive predictive factor for OS in patients with BM." (PMID 27486770, 2016). "We retrospectively reviewed the records of 134 patients with EGFR-mutated advanced lung adenocarcinoma between 2008 and 2012." (PMID 27626317, 2016). "Our study was designed to investigate the prognostic value of the 18F-FDG PET-derived parameter TLG per RECIST 1.1 criteria in patients with advanced lung adenocarcinoma stratified using EGFR mutation status." (PMID 27336755, 2016). "Some oncogene-addicted cancers will have stereotyped genomic escape mechanisms, leading to progression (for example, ABL kinase domain mutations in CML and gain of EGFR p.T790M mutation in EGFR-mutated lung adenocarcinoma)." (PMID 27784327, 2016). "Clinicopathological characteristics and disease recurrence in patients with stage I EGFR-mutated lung adenocarcinomas (univariate analyses)." (PMID 27861549, 2016). "Herein, we report a case of SCLC transformation and metastasis to the breast in a patient with lung adenocarcinoma harboring EGFR mutation during the EGFR-TKI maintenance therapy." (PMID 27488410, 2016). "Recent studies have also suggested that Ras mutations in lung adenocarcinomas were found to be associated with resistance to EGFR tyrosine kinase inhibitors (TKI)." (PMID 26791782, 2016). "The EGFR mutation rate of Cohort-I was 55.8%, which was comparable with that of Asian patients with lung adenocarcinoma." (PMID 27449093, 2016).
lung adenocarcinoma (continued). "The present study investigated the HER-2 mutation rate in lung adenocarcinoma patients in China with wild-type EGFR and its relationship to clinical characteristics and prognosis." (PMID 27793199, 2016). "With an overall median PFS of 11 months and a median overall survival (OS) of 23 months, the results compare favorably with results obtained in randomized studies using TKI in first line in EGFR mutation positive adenocarcinoma of the lung." (PMID 27032107, 2016). "Therapies like erlotinib target the key player EGFR, which is mutated in about 10% of lung adenocarcinoma." (PMID 27279498, 2016). "Results showed that DNA copy number abundances of EGFR, ERBB2, ERBB3, and ERBB4 had associations with overall survival in lung adenocarcinoma with EGFR-activating mutations." (PMID 26824984, 2016). "Even when we analyzed what was apparently the lowest reported rate of EGFR mutations (7.5 %) in a study in Norway, we see that, of 240 tumors, only 141 were actually lung adenocarcinomas, and only 11 % of patients had EGFR mutations." (PMID 27655296, 2016). "In conclusion, we found that the presence of EGFR mutations was significantly associated with early stage disease at initial diagnosis in lung adenocarcinomas." (PMID 27861565, 2016). "At present, the greatest improvement in treating lung adenocarcinoma has been achieved with EGFR TKIs because EGFR mutations can predict the efficacy of such a treatment." (PMID 27070580, 2016). "Lung adenocarcinoma with clear cell component is a rare, malignant tumor with poor prognosis and displays more frequent EGFR and KRAS mutations." (PMID 27013585, 2016). "The high incidence of EGFR tyrosine kinase domain mutation in NSCLCs has provided the rationale for successful application of a class of EGFR-TKIs for first-line lung adenocarcinoma treatment." (PMID 27285768, 2016). "In lung adenocarcinoma, the presence of Shh and Gli-1 correlated with better overall survival, showing association with EGFR overexpression, whereas TGF-ß acts as a tumor promoter by transcriptionally inducing Gli-proteins and thus mediating tumor survival." (PMID 27918595, 2016). "We used multiple logistic regression to analyze EGFR mutation status in lung adenocarcinoma patients." (PMID 27191886, 2016). "We found that the gRNA targeting the driver mutation EGFR was one of the highest-ranking candidates in the EGFR-mutant HCC-827 lung adenocarcinoma cell line." (PMID 27613601, 2016). "In another study, 20 out of 21 (95.2%) MP-predominant lung adenocarcinomas harboured EGFR (85.7%) driver mutations." (PMID 27046167, 2016). "Collectively, these results suggest that EGFR mutations correlate with the loss of ZEB1 in lung adenocarcinomas." (PMID 27456471, 2016). "Of particular importance, the system reported similar expression patterns for primary tumor samples from patients with lung adenocarcinoma (positions 1-10) with ranking attributed to the mutation pattern either in EGFR, KRAS, or ALK genes." (PMID 26967245, 2016). "High PD-L1 expression was likely to be associated with the presence of EGFR mutation in advanced lung adenocarcinoma." (PMID 25895031, 2015). "RFS of lung adenocarcinoma patients harboring EGFR mutations, KRAS mutations or ALK fusions were compared to that of wild-type patients." (PMID 26486077, 2015). "In the following study it is more interesting to study the relationship between ROR1 expression and EGFR mutation status in larger population of lung adenocarcinoma patients." (PMID 25978653, 2015). "Epidermal growth factor receptor (EGFR) mutations are the strongest response predictors to EGFR tyrosine kinase inhibitors (TKI) therapy, but knowledge of the EGFR mutation frequency on lung adenocarcinoma is still limited to retrospective studies." (PMID 26599344, 2015). "In the present study, we showed that the incidence of EGFR mutations in Taiwanese lung adenocarcinoma patients was 55.7%, which was similar to the results of PIONEER study." (PMID 25789627, 2015).
lung adenocarcinoma (continued). "From these observations, it has been postulated that mutation of the EGFR is an early event in the pathogenesis of lung adenocarcinoma." (PMID 26338423, 2015). "In lung adenocarcinoma, PD-L1 tended to be associated with mutant EGFR (PD-L1 overexpression in mutant and wild-type EGFR, 64/89 (71.9%) vs. 32/56 (57.1%), respectively; p=0.067)." (PMID 25895031, 2015). "In this study, we evaluated by FISH analyses, the MET status of 35 lung adenocarcinoma patients with EGFR gene mutations who received gefitinib therapy." (PMID 25886066, 2015). "The Iressa Pan-Asia Study (IPASS) study showed that gefitinib had high efficacy in lung adenocarcinoma patients with EGFR mutations." (PMID 26285137, 2015). "For example, activated EGFR mutations are detected in approximately 10–17% of lung adenocarcinoma patients in the United States and Europe but in approximately 30–65% of lung adenocarcinoma patients in Asia." (PMID 26134262, 2015). "Aberrant activation of the PI3K/AKT/mTOR pathway is one of the mechanisms of acquired resistance to EGFR-TKI in patients with lung adenocarcinoma carrying EGFR activating mutations." (PMID 25978653, 2015). "In unselected lung adenocarcinoma cases, EGFR mutations are present in ~15% of Caucasian cases and 30 to 50% of East Asian cases." (PMID 26332764, 2015). "We examined 181 specimens of lung adenocarcinoma tissue embedded with paraffin (76 Uighur and 105 Han patients) for mutations in the EGFR gene in exon 18-21 by the amplification refractory mutation system (ARMS) method." (PMID 25886900, 2015). "We prove that high PD-L1 expression is likely to be associated with the presence of EGFR mutation in advanced lung adenocarcinoma." (PMID 25895031, 2015). "In the Cohort 1 analysis, 987 of 1772 lung adenocarcinoma patients (55.7%) harbored activated EGFR mutations, which accounted for the majority of diver gene mutations." (PMID 25789627, 2015). "Screening for TK domain (exons 18-21) documented that 19.8% of lung adenocarcinomas were EGFR-mutated, mostly in 19 and 21 exons, according to the literature." (PMID 26807202, 2015). "Previous studies have demonstrated EGFR abnormalities, as mutations and gene copy gain, in the progression of lung adenocarcinoma." (PMID 26422230, 2015). "Lung adenocarcinoma possesses distinct patterns of EGFR/KRAS mutations between East Asian and Western, male and female patients." (PMID 26160836, 2015). "EGFR alterations in cancer can be divided mostly in two categories: mutations in exons 18–21 mainly identified in Asia lung adenocarcinoma, and gene and protein overexpression." (PMID 25953424, 2015). "We examined the mutation status of MLH1 in a larger set of EGFR L858R-positive lung adenocarcinomas." (PMID 25823662, 2015). "Results are also available from phase 3 trials (LUX-Lung 3 and LUX-Lung 6) of afatinib in patients with EGFR mutation-positive lung adenocarcinoma 33,34." (PMID 26310719, 2015). "To clarify the mechanisms by which VNR + DIF chemotherapy was favorable in the treatment of EGFR-mutated lung adenocarcinoma, we focused on the effects of VNR and 5-FU on EGFR phosphorylation." (PMID 25573239, 2015). "As far as we know, it is the first paper to identify that overexpression of miR-183 is significantly associated with EGFR exon 19 mutated lung adenocarcinoma." (PMID 26170125, 2015). "In our study (PPS population), the overall EGFR mutation frequency was 50.2%, similar to previous studies in East Asian patients, but much higher than in Caucasian lung adenocarcinoma patients." (PMID 26599344, 2015). "The aim of the present study was to investigate the impact of tissue type and content of neoplastic cells in the specimen on the quality of EGFR mutation analysis among patients with lung adenocarcinoma." (PMID 25683726, 2015). "Our aim was to investigate the clinical and pathologic characteristics of the epidermal growth factor receptor (EGFR) exon 18 mutations in East Asian lung adenocarcinomas patients." (PMID 26354324, 2015).
lung adenocarcinoma (continued). "One-hundred and three formalin-fixed paraffin-embedded (FFPE) tissues were collected from lung adenocarcinoma patients who underwent surgery and epidermal growth factor receptor (EGFR) mutation study." (PMID 26170125, 2015). "From the cohort database survey of mutant EGFR lung adenocarcinoma, we conducted this study to evaluate the response and survival in different sequence of chemotherapy/TKIs among all and different EGFR mutation subgroup patients." (PMID 26609535, 2015). "To confirm the association between CXCR4 and the EGFR-L858R mutation, we performed an EGFR mutation analysis of cancer cells in MPEs from 12 lung adenocarcinomas and analyzed the surface expression of CXCR4 by flow cytometry." (PMID 26338423, 2015). "Being less toxic, gefitinib and erlotinib have been reported to be superior to conventional cytotoxic chemotherapy in terms of RR and PFS time in lung adenocarcinoma patients with EGFR mutations such as L858R (EGFR addiction)." (PMID 26370727, 2015). "Our findings demonstrate that lung adenocarcinomas harboring the EGFR-L858R mutation exhibit increased cancer cell invasive ability and MPE formation through activation of the CXCL12-CXCR4 axis." (PMID 26338423, 2015). "In EGFR-mutated lung adenocarcinoma patients who experienced disease recurrence, treatment with EGFR TKIs was an independent predictor of better overall survival (HR = 0.299, 95% CI: 0.172–0.519, P < 0.001)." (PMID 26486077, 2015). "We also indicated that EGF stimulated a significant increase in the expression of CXCR4 in lung adenocarcinoma cells harboring the EGFR-L858R mutation." (PMID 26338423, 2015). "The mutations in EGFR exon 18 were observed in 2.8% of 1,201 lung adenocarcinomas and 4.6% of patients with EGFR mutations." (PMID 26354324, 2015). "In summary, this study reveals some of the key molecular changes associated with EGFR mutant lung adenocarcinomas that transform to SCLC upon acquisition of resistance to EGFR TKI." (PMID 25758528, 2015). "They account for about 90 % of all EGFR mutations reported in lung adenocarcinoma and are known to be sensitive to the EGFR-TKIs gefitinib, erlotinib, or afatinib." (PMID 26022577, 2015). "The PIONEER study (NCT01185314) is a prospective molecular epidemiology study in Asian patients with newly diagnosed advanced lung adenocarcinoma, aiming to prospectively analyze EGFR mutation status in IIIB/IV treatment-naïve lung adenocarcinomas in Asia." (PMID 26599344, 2015). "LUX-Lung 2, a single-arm phase II study in 129 patients with lung adenocarcinoma containing activating EGFR mutations within exons 18-21, showed antitumor activity after treatment as first or second line with afatinib daily 40 or 50 mg." (PMID 25674538, 2015). "In this study, we retrospectively investigated the frequency, molecular spectrum and clinicopathologic characteristics of patients with EGFR exon 18 mutations in a large cohort of patients with lung adenocarcinomas." (PMID 26354324, 2015). "In HCC827 and H1975 human lung adenocarcinoma cells that harbor mutant EGFR (del19 and L858R/T790M mutations, respectively), Gab1 was constitutively tyrosine phosphorylated and bound Shp2." (PMID 25730908, 2015). "We detected the KRAS and EGFR mutation as well as the KIF5B-RET fusion gene in primary lung adenocarcinomas." (PMID 26268359, 2015). "To investigate the association of IL-8 levels with EGFR TKIs responsiveness, we collected peripheral blood samples from 75 stage IV lung adenocarcinoma patients with EGFR-mutation positive tumors and receiving EGFR-TKIs only as the first-line treatment." (PMID 25871388, 2015). "In conclusion, in the present study we documented that CRBP-1High expression in lung adenocarcinomas associates with a poor survival and increased tumor grade, likely influencing the activity of Akt/EGFR gene pathways." (PMID 26807202, 2015).